ITGAM (integrin subunit alpha M)
Diseases named in the same sentence as ITGAM in open-access papers (continued):
Sharing a sentence is not in itself a finding about the gene and the disease.
tumor (continued). "Among them, ITGB3+ exosome were enriched in Integrin α L, which could promote the proliferation, migration and invasion of tumor cells; whereas ITGAM+ exosome exhibited inhibition of tumor progression and may originate from macrophages." (PMID 41601682, 2026). "Moreover, IHC staining of the tumor tissues derived from shNKX2‐1/LL2 cells orthotopically implanted into mouse lungs also showed elevated expression of ITGAM, CEACAM8, ELANE, and CXCR2 as compared to the control." (PMID 39113226, 2024). "A recent study reported that ITGAM regulates myeloid cell polarization and tumor growth." (PMID 37375208, 2023). "We found that the mRNA expression of C1QA, C1QB, C1QC, C5AR1, C3AR1, C1QR (CD93), CR1, CR2, CR3 (ITGAM), and CR4 (ITGAX) were positively associated with almost all kinds of tumor immune cells, including CD8+ T cells, CD4+ T cells, B cells, macrophages, monocytes and DCs." (PMID 34813686, 2022). "Our data demonstrated that GPX8 was correlated with mRNA expression of immune markers of CD8+ T cells (CD8B), CD4+ T cells (CD4), T cells (CD3D), macrophages (CD68 and ARG1), neutrophils (ITGAM and CCR7), dendritic cells (NRP1), NK cells (B3GAT1), and tumor-associated fibroblasts (FAP)." (PMID 36061208, 2022). "It should be noted that ITGAM also has low expression in the B cells of tumor samples." (PMID 33777800, 2021). "Interestingly, although major macrophage-specific mRNAs (CD68, CD14, and ITGAM) were relatively unchanged, the mRNAs associated with an M2 phenotype (CSFR1, CD163, MS4A4A, and CRC1) were decreased, suggesting a change toward a more M1, anti-tumor status." (PMID 38744944, 2024). "Pharmacological activation of CD11b, ITGAM, using the small molecule agonist leukadherin one enhances pro-inflammatory macrophage polarization, effectively suppressing tumor growth in murine and human cancer models." (PMID 40809316, 2025). "This phenomenon is caused by the increased expression of the CD27, integrin subunit alpha M (ITGAM), and CCL5 genes within tumor compartments." (PMID 39802954, 2024). "Many signals favoring tumor cells were significantly activated in C2, such as integrin-related signals (COL9A3 − (ITGA2+ITGB1), JAM3 − (ITGAM+ITGB2), COL6A1 − (ITGA1+ITGB1)), immune suppression signals (CD99 − PILRA), etc.." (PMID 39391717, 2024). "Subsequently, we attempted to perform immunohistochemistry (IHC) staining for NRGs (CYBB, ITGB2, ITGAM, LILRB2, TLR2, and TLR7) in kidney sections from ANCA-GN patients and age- and sex-matched ccRCC patients with adjacent non-tumor tissues." (PMID 37465687, 2023). "Consistently, the features for suppression of anti-tumor immunity were dominantly elevated in the CDC20-high group, such as BTLA, CTLA4, CD4, ITGAM, C4B, CD163, and CD206." (PMID 37528490, 2023). "According to the ITGAM (Integrin alpha M chain) and CLU (Clusterin) were differentially expressed in serum exosomes among different groups as well as tumor tissues and adjacent tissues." (PMID 35291954, 2022). "We observed an overexpression of neutrophil intracellular marker protein (MPO) and cell surface marker proteins (CEACAM8, ITGAM and ITGB2) in early stage GBC in comparison to GSD (non-tumor controls) suggesting neutrophil infiltration in tumor tissue." (PMID 36686780, 2022). "We found that the infiltration of mDCs in tumor tissues can be promoted by the expression of ICAM1 and interaction with ITGAM expressed in macrophages." (PMID 34876143, 2021). "For the validation of this analysis, the GEPIA expression level of the hub genes were also employed and gene- ITGAM, ITGAX, PTPRC along with STAT3 were found in lower expression levels in tumor cells." (PMID 33946372, 2021). "Conversely, ITGAL and ITGAM were strongly decreased in LMNA+ cells and this is in accordance with the anti-tumour effects reported in the literature for these two integrins." (PMID 34680461, 2021).
tumor (continued). "On the other hand, gene expression analyses confirmed that proteins related to the complement activation, such as C1QA, SERPING1, A2M, ITGAM and ITGB2, were significantly overexpressed in P3 tumours, compared to P1 and P2 subtypes." (PMID 31560832, 2019). "Others include tumour-infiltrating myeloid cells (TIMs), CD11b (ITGAM) (+) TIMs, and CD11b+ myeloid-derived suppressor cells (MDSC)." (PMID 26066800, 2015). "Compared to naïve HL-60 human promyelocytic leukemia cells, which cannot be engulfed by tumor cells, differentiated HL-60 (dHL-60) neutrophils, which can be engulfed by tumor cells, express several integrin family genes, such as ICAM-1, ITGAM, ITGB2, ITGAX, and ITGAV, at higher levels." (PMID 39941753, 2025). "In addition, enhanced expression of proteins related to antigen processing and immune activation, including HLA-DRA, ITGAM, and C1QC, reflected a strong inflammatory phenotype within the tumor tissue." (PMID 41480141, 2025). "EGFR and IDH1 were highly expressed in tumor cells, FAP and COL1A1 were confined to fibroblasts, CD68 and ITGAM marked macrophages, PECAM1 and CDH5 identified endothelial cells, OLIG2 and MOG were specific to oligodendrocytes, while CD4 and CD3D defined T-cell subsets." (PMID 41208987, 2025). "We observed that MFAP5 + fibroblasts were the main senders that could release complement C3 to interact with the receptors ITGAM/ITGB2, ITGAX/ITGB2, and C3AR1 of C1QC + macrophages in tumor tissues, thus activating the complement system." (PMID 37344903, 2023). "For ITGAM, we found that there were weak positive and negative expressions in the adjacent tissues while strong positive and positive expressions in the tumor tissues." (PMID 35291954, 2022). "For deciphering the precise influence of tumor-associated macrophages (TAM) after X-body treatment, cells with high transcript of CD11b (ITGAM), F4/80 (ADGRE1) and CD115 (Csf1r) were defined as macrophages which accounted for nearly half of the tumor-infiltrating immune cells." (PMID 36451853, 2022). "Using scRNAseq data from patient samples of primary and recurrent GBM (GSE154975), we identified multiple cell types based on markers from the original study: macrophages (ITGAM), T cells (CD3E), Tregs (CD4, CD3E, FOXP3), low-reads/dying cells (MALAT1), and tumor/normal brain cells (GFAP, SOX2)." (PMID 36591276, 2022). "The interaction of neutrophil integrin CD11b (also known as ITGAM) with intercellular adhesion molecule 1 (ICAM-1) on cancer cells and platelet-induced clot formation further promote tumor cell adhesion." (PMID 30355585, 2018). "To determine whether the greater MHC-II gene expression in CB tumors correlated with tumor or immune cells, we evaluated the dendritic cell genes ITGAX and FLT3 and the macrophage gene ITGAM, corresponding to the CD11b protein expressed on the surface of macrophages." (PMID 34548479, 2021). "Moreover, these genes may play important roles in promoting tumor angiogenesis (CXCL13, ZAP-70, and CCL19), tissue remodeling (ITGAM and ITGB2), and immunosuppression (CD4 and IL-10) in cancer cell lines or samples." (PMID 32509861, 2020). "Also, Tregs from NI ad I TDLN share CD58, ITGAM, MCAM, CEACAM4, SELPLG, and HMMR expression, which could ensure recirculation among TDNLs; and Tregs from I TDLN and tumor Tregs share ICAM1 expression, which could be responsible for the migration among tissues with presence of tumor cells." (PMID 32601304, 2020). "Among them, CYBB, ITGAM, and PLEK showed significantly negative correlations with tumor purity (ρ = -0.555, -0.514, and -0.44), suggesting their potential as markers of the immune microenvironment." (PMID 40895569, 2025). "Some M1 markers (IL1A, IL1B, CD86), M2 markers (CCL18, MRC1/CD206, CSF1R), and TAM markers (HLA-DR, IL1RN, CD163, ITGAM, SIGLEC1/CD169) were highly expressed on both tumor and non-tumor macrophages." (PMID 33918618, 2021).
tumor (continued). "Spatial transcriptomics of TAMs infiltration in NSCLC reveals that TAMs enrichment in the TME is relevant to tumor cell resistance to ICB immunotherapy regardless of its PD-L1 status, which is mediated by CD27, ITGAM, and CCL5 gene expression upregulation within tumor compartment." (PMID 40083710, 2025).
infection (825 papers, 2004 to 2026). The state of being infected such as from the introduction of a foreign agent such as serum, vaccine, antigenic substance or organism. "Signalling mediated by TLR4 activates the synthesis of ITGAM/CD11b, which is essential for the migration and adhesion of polymorphonuclear leukocytes to infection sites." (PMID 35264251, 2022). "There were statistically significant associations between positive infection status and four of the five genes: IRF-9 (OR = 1.750, 95% CI = 1.16–2.638), ITGAM (OR = 1.533, 95% CI = 1.047–2.244), PSTPIP2 (OR = 2.191, 95% CI = 1.293–3.711), and RUNX1 (OR = 1.974, 95% CI = 1.069–3.646)." (PMID 36900096, 2023). "Notably, the role of each of the five genes (ITGAM, IRF-9, LY6E, PSTPIP2, and RUNX1) has been linked to response to infection in the literature." (PMID 36900096, 2023). "Down-regulation of ITGAM may therefore help protect cells from infection with mycobacteria." (PMID 19239680, 2009). "Levels of CD11b (CR3A/ITGAM [integrin alpha M]), mediating leukocyte adhesion, and the degranulation marker CD66b (CEACAM8) were also increased compared to the mock-infection results, with significantly elevated CD66b levels seen upon C. albicans infection." (PMID 33024045, 2020). "Myeloid dendritic cells in dormant infections also showed notable differences in mRNA expression, affecting neutrophil recruitment (C1QA, C1QB, ITGAM), immune checkpoint regulation (IFITM2, IFITM3, CST7, THBS1), and T-cell response (VISIG4, V-set immunoglobulin domain containing 4)." (PMID 39563367, 2024). "IRF-9 (OR = 1.750, 95% CI = 1.16 to 2.638), ITGAM (OR = 1.533, 95% CI = 1.047 to 2.244), PSTPIP2 (OR = 2.191, 95% CI = 1.293 to 3.711), and RUNX1 (OR = 1.974, 95% CI = 1.069 to 3.646) had a significant expression with positive infection status." (PMID 36900096, 2023).
cancer (383 papers, 2007 to 2026). A tumor composed of atypical neoplastic, often pleomorphic cells that invade other tissues. "Reports state that TYROBP, TLR4, and ITGAM are involved in several cancer-immune microenvironment-associated pathogeneses, including OS23." (PMID 34588497, 2021). "We also queried the effect of cancer cells on the expression of ITGAM and other mRNAs encoding leukocyte cell surface proteins." (PMID 33086476, 2020). "Specifically, we found that CTNNB1 mutated carcinomas showed significantly downregulated levels of ITGAL, ITGAM, and ITGB2, which are involved in leukocyte transendothelial migration." (PMID 41227323, 2025). "Of note, consistent with the co-amplification profile of ITGAD, ITGAL, ITGAX, and ITGAM, we observed similar dysregulation patterns for them in cancers (belonging to one sub-cluster), validating our analytic pipeline." (PMID 39436262, 2024). "Recent findings indicate that ITGAM modulates angiogenesis through cytokine expression control in murine and human cancer models." (PMID 37816585, 2023). "The authors further suggested that ITGAM negatively regulates immune suppression; therefore, it is a potential target for cancer immunotherapy." (PMID 37375208, 2023). "For the myeloid-derived cancer cell lines, we identified specific surface markers (e.g., ITGAM, ITGAX, CD68, CD86) usually present on monocytes, neutrophils, and macrophages, positively contributing to the BAY-155, EPZ-5676, and Brequinar group." (PMID 31253180, 2019). "Most of the validated genes, such as IL15, ITGAM, PDK4, and IRX5, have been implicated in AML progression and/or as survival predictors in several types of cancers." (PMID 31740623, 2019). "Several studies have implicated NME2 as a regulator of genes implicated in cancer progression such as c-MYC, PDGF-A, ITGAM and telomerase." (PMID 25249619, 2014). "Moreover, potential roles for ITGAM in various malignant tumors have also been reported." (PMID 33104706, 2020). "The bar charts show the total alteration frequency of six hub genes (CD36, CXCL12, CXCR4, CYBB, ITGAM, PLEK) in pan-cancer." (PMID 40895569, 2025). "ITGAM and ITGB2 are subunits of integrin, and these cell adhesion-related molecules are closely related to cancer cell invasion and metastasis." (PMID 36615183, 2023). "In myeloid cells, the top 50 pan-cancer central genes included seven genes involved in myeloid cell differentiation (CD4, FCER1G, IRF8, TYROBP, TLR2, TREM2 and ITGAM), but only two of them (FCER1G and TYROBP) were found among the top 50 DEGs." (PMID 36350625, 2023). "The “Target” run with ANGPTL3 as a target gene shows that altered genes of various cancer types including MAPK1, CASP5, COL3A1, ITGAM and TMEM59L change the expression of ANGPTL3." (PMID 37375208, 2023). "This study provides plentiful of not only clinical but also experimental evidence that cancer cell-derived ITGB3+ exosomes mediated CRC progression and metastasis and macrophage-derived ITGAM+ exosomes mediated CRC suppression." (PMID 37040507, 2023). "Although this finding is not altogether surprising as MDSC levels are often increased in patients with cancer, we have formally shown that MDSC accumulation occurs concurrently with the expression of ITGAM in HCC." (PMID 33860040, 2021). "Because both analyses showed that OLFML2B was positively correlated with macrophage content, we input cancer-related macrophage markers into the web tool “CellMarker” and obtained experimentally verified markers: CD14, CD68, CD163, CSF1R, ITGAM, and MRC1." (PMID 34868901, 2021). "ITGAM and AAK1 have not been previously reported to be related to cancer, and our study is the first to suggest that they could be used as new prognostic markers of DLBCL." (PMID 33692952, 2021).
bacterial infection (29 papers, 2010 to 2025). "On the other hand, other genes, such as Integrin Subunit Alpha M (ITGAM), have been shown to regulate neutrophil migration and mediate the adhesion of neutrophils to pathogens leading to pathogen clearance in bacterial infections." (PMID 36900096, 2023).
neurodegenerative disease (10 papers, 2013 to 2023). A disorder of the central nervous system characterized by gradual and progressive loss of neural tissue and neurologic function. "In the gene expression profiles of purified microglia isolated at autopsy of individuals without neurodegenerative disease, microglial Lag3 was expressed at levels similar to known microglial marker ITGAM (CD11B), with confirmation at the protein level using DAB staining and immunofluorescence." (PMID 36768798, 2023).
renal disease (8 papers, 2015 to 2025). "Previous studies of ITGAM variant rs1143679 had found this allele to be associated with increased risk of renal disease, discoid rash, and immunological manifestations." (PMID 31659207, 2019). "From these, the most significant associations have been detected between renal disorder and genetic variation in the ITGAM and STAT4 genes, which have been also associated with discoid rash and oral ulceration, respectively." (PMID 28619073, 2017). "Conversely, the reported association between renal disorder and ITGAM and STAT4 genes was not replicated." (PMID 28619073, 2017).
cardiovascular diseases (4 papers, 2022 to 2025). "An increase in calcifications due to ITGAM dysfunction might play a role in the increased risk of cardiovascular diseases observed among SLE patients." (PMID 37239465, 2023).
vasculopathy (3 papers, 2013 to 2025). "ITGAM is associated with SLE and is found to be upregulated in KD patients with vasculopathy." (PMID 35615376, 2022).
ITGAM also shares sentences with these, for which no sentence is quoted: colitis (147 papers); liver fibrosis (40); influenza infection (38); Splenomegaly (29); Cerebral ischemia (24); inflammation (24); Granuloma (23); brain tumors (21); experimental autoimmune encephalomyelitis (20); myocarditis (18); ischemia (17); peritonitis (17); prostate carcinoma (17); acute myeloid leukemia (15); allergic asthma (13); Allergy (13); Hepatitis (13); hepatocellular carcinoma (13); malaria (13); multiple sclerosis (13); myeloid leukemia (13); endotoxemia (12); leukocytosis (12); liver (12); parasitemia (12); Parkinson disease (12); inflammatory bowel disease (11); metastatic tumors (11); prostate tumor (11); Hyperglycemia (10).
A further 458 diseases each share a sentence with ITGAM in 9 papers or fewer.